IL4 (interleukin 4)
Diseases named in the same sentence as IL4 in open-access papers (continued):
Sharing a sentence is not in itself a finding about the gene and the disease.
Granuloma (continued). "IL-4 also augments fibroblast growth and collagen production during granulomas formation, a characteristic mark of the chronic development of ALA, a reaction trying to contain the infection." (PMID 26090442, 2015). "We also demonstrated that the Th1 cytokines, IFN-γ and IL-2, were detected in early granulomas, while Th2 cytokines, IL-4 and IL-10, were detected in more mature granulomas." (PMID 25530957, 2014). "Since Th2 cytokines, IL-4 and IL-10, are known to downmodulate granuloma formations, we also measured their levels in granulomas from the two groups of mice." (PMID 25530957, 2014). "Using a commercial kit to detect typical Th1/Th2 cytokines, we compared the levels of IFN-γ, TNF-α, IL-2, IL-4, and IL-5 in lung homogenates 14 days after granuloma induction and in serum samples collected 1, 5, 14 and 18 days after granuloma induction." (PMID 22013486, 2012). "Antigens secreted by these eggs induce a Th2 response, involving secretion of interleukin-4 (IL-4), IL-5 and IL-13 and the eventual development of granulomas." (PMID 23145202, 2012). "We have previously demonstrated that epithelioid cell surrogates (ECs) derived from primary murine peritoneal macrophages through a process of differentiation induced by IL-4 overlap several features of epithelioid cells found in granulomas." (PMID 21731758, 2011). "They mediate significant levels of antigen-specific Th2 suppression in vivo including reduced IL-4 production, eosinophil recruitment, collagen production, and an overall reduction in the size of egg-induced granulomas in the large intestine." (PMID 21858239, 2011). "Granulomas in Irf5-/- mice are characterized by an increased IL-4 and IL-10 response and concomitant low iNOS expression." (PMID 21253574, 2011). "Our results showed that the lungs from CFA-inoculated mice treated with anti-IL-4 mAb showed smaller granulomas, milder disruption of the pulmonary parenchyma and reduced infiltration of inflammatory cells in comparison with CFA- IgG-treated control mice." (PMID 21731741, 2011). "In the schistosome pulmonary granuloma model, studies conducted with IL-4−/−, IL-13−/−, and IL-4−/−/IL-13−/− double knockout mice demonstrated that egg-induced granuloma formation is dependent on both IL-4 and IL-13." (PMID 19381262, 2009). "Studies with the helminth egg-induced granuloma model showed that Retnla expression was strongly dependent on the Th2 cytokines IL-4 and IL-13 and negatively regulated by IFN-γ." (PMID 19381262, 2009). "While the presence of necrosis did not significantly influence the grade of IL-12 mRNA positivity, IFN-γ, TNF-α and IL-4 mRNA expression were markedly upregulated in necrotic granulomas." (PMID 19156215, 2009). "Immunohistochemistry of Mtb-laden lungs show increased IFN-γ, IL-12, IP-10, and TGF-β in granulomas and areas with pneumonitis with reductions in IL-10 and IL-4 compared to controls." (PMID 19753300, 2009). "Notably, mice that did present with granulomas appeared to have changes to lymphoid follicles and enhanced humoral responses, indicated by increased IL-4, IL-5, and IL-10 in splenocyte supernatants." (PMID 40375983, 2025). "Similarly, the expression of TGF-β in M2 MΦs and neutrophils, and the expression of IL-4 in lymphocytes, was observed diffusely in the lung parenchyma, with limited presence in immature and mature granulomas." (PMID 41189022, 2025). "Inhibition of IL-4 and IL-13, key players in the differentiation and activation of Th2 cells, may shift the Th1/Th2- ratio toward an excessive Th1-mediated response, granuloma formation, and drug-induced (neuro)sarcoidosis reaction." (PMID 35795795, 2022). "Type-2 cytokines, such as IL-5, IL-4, and IL-13, are responsible for the recruitment and activation of immune cells involved in granuloma formation, whereas IL-10 has been related to the granuloma modulation." (PMID 31886307, 2019). "IL-4 was the most intensely expressed cytokine in both cysts and granulomas." (PMID 29898177, 2018).
Granuloma (continued). "In granulomas, IL-4 expression was significantly higher than IL-6 (p=0.001) and TNF-α (p=0.001)." (PMID 29898177, 2018). "In general, IL-4 was the most expressed mediator in both cysts and granulomas." (PMID 29898177, 2018). "However, in treated animals it was observed greater production of IL-4 compared with the untreated group, concomitant to the earlier presence of mature granulomas in the livers of animals that received the chemokine (data not shown)." (PMID 28767981, 2017). "The development of granulomas from S. mansoni exposure is not impaired in IL-4-deficient mice, as other Th2 cytokines remain elevated." (PMID 26962470, 2015). "Based on our observation that IL-10 was greatly elevated in the M2 macrophage model induced by IL-4, it can be speculated that the inhibitory role of M2 macrophages in preventing the formation and development of granulomas may be partially mediated by IL-10." (PMID 26091535, 2015). "We have previously shown that epithelioid cell surrogates (ECs) derived from primary murine peritoneal macrophages through a process of differentiation induced by recombinant IL-4 (rIL-4), overlap several morphological and functional features of epithelioid cells found in granulomas." (PMID 21731758, 2011). "Indeed, the depletion of either cytokine alone reduced granulomatous inflammation by half, while the simultaneous depletion of both IL-4 and IL-13 nearly ablated granuloma development." (PMID 19381262, 2009). "IL-4, IL-5, and IL-13 are then released, recruiting pro-inflammatory monocytes, neutrophils, eosinophils, hepatic stellate cells (in the liver), and macrophages around the eggs to form granulomas, collagen deposition, and fibrosis, leading to the destruction of the eggs." (PMID 38338980, 2024). "It is also conceivable that IL-4/IL-13 production in the perivascular adventitial space—likely more relevant to vascular remodeling—may be masked by whole-lung assessments such as IL-4/IL-13 levels in whole lung lysates, and analysis of peri-egg granulomas." (PMID 35417453, 2022). "Thus IL-4 has been shown to play a major part in the development of granuloma and fibrosis in around S. mansoni eggs in the liver, but its influence was more on the growth of granuloma formation in the lungs of the same animals." (PMID 31024947, 2019). "Pulmonary IL-4 expression was hardly detected in untreated Wt and HIV mice but strongly induced in granulomas of egg-treated mice, and mostly in perivascular areas and to a lesser degree in intravascular locations." (PMID 35954255, 2022). "The parenchymal architecture of the lungs of P10+DODAB-treated animals was largely preserved with only a few granulomas present, and tissue cytokine analysis showed a Th1 cytokine profile with augmented levels of IL-12, IFN-γ and TNF-α, and low levels of IL-4." (PMID 34073466, 2021). "Immunohistochemistry of TB granulomas consistently showed IL-12p40 in CD8+ cells; 75% of granulomas were positive for both IFN-γ and IL-12, and 4/7 TB patients expressed IL-4 and IFN-γ in granulomas." (PMID 23527200, 2013). "IL-4 is a Th2 cytokine which increases TNF-α toxicity thereby aggravating tissue damage and inducing fibrosis of granuloma leading to enhanced immunopathology." (PMID 24147054, 2013). "The induction of IFNγ and IL-12 and the depletion of IL-4 producing NK cells has been attributed to TDM as well as a role, along with IL-6 and TNFα, in stable granuloma formation." (PMID 22738036, 2012). "Blockade of IL-4 in PPD-bead granuloma models in wild-type mice results in augmented IFN-γ production, and blockade of both IL-4 and IL-13 augments granuloma size." (PMID 21655295, 2011). "Additionally, we observed an enhanced expression of IL13Rα1, Jak3, and STAT6 in macrophages within CS granulomas and the increased phosphorylation of Jak3 and STAT6 are indicative of an activation of anti-inflammatory IL4/IL13 signaling pathways." (PMID 40521183, 2025).
Granuloma (continued). "The reduction of granuloma size and granuloma area by ZLE in our study may be related to its role in the upregulation of Th1 interferon-gamma cytokine and declines of Th-2 mediated cytokine IL-4 which leads to a reduction of granuloma size." (PMID 37339146, 2023). "Furthermore, inflammatory cytokines, which present high levels at the beginning of granuloma formation, such as IFN-ɣ, IL-2, IL-4, MCP-1, and TNF-α, are important factors in reducing the spread of the bacteria." (PMID 34843474, 2021). "We confirmed that S. mansoni eggs induced eosinophilic granulomas in the lung and typical type 2 inflammation with high levels of soluble schistosome egg Ag (SEA)-specific IgG1 and IL-4 production upon SEA restimulation of the dLN." (PMID 30375396, 2018). "IL-2 was detected in the same level in lung homogenates of normal and experimental groups, and the low levels of IL-4 detected in lung homogenates of immune and tolerant mice did not correlate with the size of their granulomas." (PMID 22013486, 2012). "However, different cytokines including IL-4, TNF-α, IL-10, and IFN-γ are produced during the course of granuloma formation." (PMID 22013486, 2012). "Since no functional connection between IL-4/IL-13 and the development of granuloma necrosis in TB patients was available, we previously analyzed the association of gene variants in the common receptor subunit IL4RA and disease severity in a large patient TB cohort." (PMID 34871095, 2022). "Because IL-4 and IL-13 are hardly expressed after M. tuberculosis infection in wild-type mice, which do not form centrally necrotizing granulomas, we hypothesized that an increase in IL-13 expression leads to the development of necrotic lesions." (PMID 34871095, 2022). "It is therefore possible that the upregulation of IL-4 seen in non-necrotic granulomas may be due, in part, to an upregulation of the splice variant." (PMID 19156215, 2009). "Thus, it is possible that the role of IL-4 depends on whether liver abscesses develop or not, so contributing to the formation of granulomas at later stages if ALA develops or decreasing excessive inflammation at earlier stages." (PMID 26090442, 2015). "Granulomas were characterised as necrotic or non-necrotic, graded histologically and investigated for the mRNA expression of IL-12, IFN-γ, TNF-α and IL-4 by in situ hybridisation." (PMID 19156215, 2009). "Their results showed that IL-4 positive granulomas tended to be non-necrotic whereas all necrotic granulomas were TNF-α positive and negative or weakly positive for IL-4 and IFN-γ." (PMID 19156215, 2009).
Pruritus (69 papers, 2016 to 2026). Pruritus is an itch or a sensation that makes a person want to scratch. "Clinically, elevated IL-4, IL-13, and IL-31 are implicated in the pruritus seen in MF, with IL-31 levels correlating with both disease progression and symptom severity." (PMID 40864740, 2025). "Among these, IL-4 and IL-13 have been identified as central pathogenic mediators that induce inflammation, impair skin barrier integrity, and provoke pruritus." (PMID 40918538, 2025). "Recently, several cytokines, including TSLP, IL-4/13, and IL-31, have been reported to be involved in AD-associated pruritus, and biological agents targeting these cytokines have been shown to improve pruritus in AD patients." (PMID 38590314, 2024). "IL-4, IL-13, and IL-31 are implicated in pruritus, offering therapeutic targets with dupilumab, tralokinumab, lebrikizumab, and nemolizumab." (PMID 38398754, 2024). "Our study focused on investigating ex vivo skin biopsies in AD (n = 17), CNPG (n = 14) and healthy controls (HC; n = 10), examining the gene expression landscape of interleukins linked with pruritus (IL-13, IL-4, IL-31) and their corresponding receptors." (PMID 39126011, 2024). "In a murine model, injection of IL-4 caused scratching, suggesting that IL-4 induces pruritus in mice." (PMID 37465674, 2023). "IL-4 and IL-33 are also found to induce the secretion of IL-31, which is one of the elements alongside with the discussed interleukins, causing pruritus in AD and in CTCL—but the data are ambivalent concerning lymphomas." (PMID 34948183, 2021). "Furthermore, cytokines like IL‐4 and IL‐31 can sensitize peripheral nerves causing them to mediate pruritus sensation." (PMID 37506153, 2023). "Although pruritus provoked by IL-31 may occur independently of mast cells, IL-4 causes overexpression of IL-31 in lymphocytes and mast cells." (PMID 36983094, 2023). "Other cytokines cause pruritus and are involved in the pathogenesis of AD, namely IL-4 and IL-13." (PMID 33923629, 2021). "AD is characterized by increased sensitization to IgE and increased immunological activities of Th2, leading to the production of interleukin (IL)-4, IL-13, IL-5, IL-31, and IL-10 and causing intense pruritus, xerotic skin, erythema, edema, erosion, and lichenification." (PMID 34253801, 2021). "Several cytokines such as IL-4 have been reported to be involved in AD-associated pruritus." (PMID 32349329, 2020). "In response to associated pruritus, there is prominent scratching behavior that leads to basophil-dependent IL-4 upregulation, but may lead to increased expression of the IL-13-decoy receptor IL-13RA2 and interruption of the IL-4/IL-13 signaling cascade as well." (PMID 39126011, 2024). "Th2 cytokines, such as interleukin-4 (IL-4) and interleukin-13 (IL-13), play a major role in orchestrating the inflammatory cascade, contributing to the hallmark features of AD both in the acute and chronic phases, including pruritus and eczematous skin lesions." (PMID 37892713, 2023). "IL-4 and IL-13 play key roles in the development of AD symptoms, namely, decreased integrity and barrier function of the skin and level of peptides associated with antibiotics, which further cause skin barrier abnormalities such as pruritus, xerosis, blister, pigmentation, and lichenification." (PMID 34253801, 2021). "These pathways include cytokines, such as IL-4, IL-13, IL-31, and TSLP, and chemokines, such as CCL1, CCL13, and CCL17, which have been implicated in barrier disruption, pruritus, and immune cell recruitment in AD." (PMID 41583462, 2025). "Several cytokines, including TSLP, IL-13, IL-31, and IL-4, are involved in pruritus, one of the most prominent features of AD." (PMID 40429704, 2025). "In human AD, IL-4 and IL-13 promote IgE synthesis and barrier dysfunction, IL-31 induces pruritus via neuronal activation, and TGF-β1 mediates regulatory control." (PMID 41227548, 2025).
Pruritus (continued). "Th2 cytokines such as interleukin (IL)-4, IL-13, and IL-31 promote inflammation and pruritus, whereas regulatory cytokines including transforming growth factor-β1 (TGF-β1) help preserve immune homeostasis." (PMID 41227548, 2025). "Interleukin (IL)-4, IL-13, and IL-31 play crucial roles in pruritus; therefore, their inhibition is a key therapeutic strategy." (PMID 40568299, 2025). "IL-4 is central to the activation of mast cells and basophils, which are key mediators of inflammatory responses such as urticaria and pruritus—responses commonly seen in tick-resistant hosts." (PMID 40429876, 2025). "The findings suggest a pivotal role of IL-4 and IL-13, along with IL-13RA1, in pruritus pathogenesis in both entities, while IL-13 upregulation in AD is countered by IL-13RA2." (PMID 39126011, 2024). "Research reports examining cytokines in the skin of patients with ICI-induced cutaneous symptoms have found increased production of Th2 cytokines such as IL-4, IL-5, and IL-13 in cases of urticaria, pruritus, and eczema." (PMID 39200350, 2024). "Regarding pruritus, IL-4 and IL-13 are suggested to act on IL-4Ra expressed on peripheral nerves, transmitting chronic pruritus through the Janus kinase (JAK) 1 signaling pathway." (PMID 38590314, 2024). "Subsequently, the actions of IL-4 and IL-13 drive the production of IgE, whereas IL-31 induces pruritus." (PMID 39717308, 2024). "IL-31 is a key player in the pathogenesis of pruritus, both in the acute and in the chronic stages, and its signaling pathway is closely regulated by IL-4 and IL-13." (PMID 38398754, 2024). "Further, correlation analyses elucidate the intricate connections between IL-4, IL-13 receptors, and pruritus perception, shedding light on their potential role in peripheral sensitization." (PMID 39126011, 2024). "The advanced stages of CTCL, with typical severe pruritus, shift toward a predominant Th2-cell microenvironment releasing cytokines such as IL-4, IL-5, or IL-31 that have gained attention in other itching inflammatory disorders." (PMID 37874473, 2023). "IL-4 transgenic mice: Transgenic mice overexpressing IL-4 exhibit spontaneous pruritus and chronic dermatitis at 4 months of age." (PMID 36993982, 2023). "The activation of sensory neurons by IL-4 is a significant contributor to the development of chronic itch, which is a disruption of the protective response." (PMID 37762597, 2023). "Nevertheless, additional research has demonstrated that IL-4 and IL-13 can both directly activate pruritus in mice, and that applying mixtures of these mediators even increased the induction of itch." (PMID 36983094, 2023). "In this regard, it has been shown recently that targeting IL-13 and IL-4 using the monoclonal antibody dupilumab resolves pruritus and inflammatory skin lesions in BP, indicating a role of neuroimmune interaction mechanisms with immune cells." (PMID 36979421, 2023). "According to a recent study, IL-4 increased IL-31/IL-31 receptor signaling, which is crucial for the pathophysiology and transmission of pruritus in AD." (PMID 36983094, 2023). "The pathogenesis of AD and pruritus in AD patients are both significantly influenced by the cytokines IL-4 and IL-13." (PMID 36983094, 2023). "In other pruritic diseases, notably in atopic dermatitis, research advances elucidating the mechanisms of pruritus involving IL‐4, −13, and − 31 has resulted in the development of targeted therapies that revolutionized current clinical treatment." (PMID 36477831, 2023). "These itch‐specific iNCs were responsive to AD driver cytokines (IL4/IL‐13) as indicated by calcium imaging." (PMID 35111948, 2022). "IL-4 is known to induce pruritus by inducing the synthesis of IgE and activating mast cells, which, in turn, contributes to the progression of AD." (PMID 36670888, 2022). "The expression and release of IL-31 induced by IL-4 in Th2 cells are a recently identified cytokine with a well-defined role in the pathogenesis of pruritus." (PMID 35563259, 2022).